IL27 (interleukin 27)
Diseases named in the same sentence as IL27 in open-access papers (continued):
Sharing a sentence is not in itself a finding about the gene and the disease.
atherosclerosis (continued). "While the data from clinical studies may suggest that IL-27 has pro-atherogenic effects, IL-27 receptor knock out mice that are prone to develop atherosclerosis have increased atherosclerosis and inflammation." (PMID 29176764, 2017). "Moreover, in terms of atherosclerosis development, IL27 is known to induce in HUVECs the upregulation of the chemokines CXCL9 and CXCL10, implicated in the transendothelial cell migration." (PMID 26663990, 2015). "A pathway analysis of primary tissue from different coronary atherosclerotic lesion demonstrated an upregulation of IL27 in the early developed lesions of atherosclerotic material, which emphasizes an important role of IL27 in the development of atherosclerosis." (PMID 26663990, 2015). "IL-27 is a member of the IL-12 family of cytokines that, in contrast to IL-12 and IL-18, limits the intensity and duration of T cell responses, and limits atherosclerosis in animal models of atherosclerosis." (PMID 25699211, 2015). "Thus, IL-27 potentially plays an important role in promoting the development and progression of atherosclerosis." (PMID 22911112, 2012). "Further studies are required to elucidate whether IL-27 affects the development and progression of atherosclerosis, which may provide insights into novel therapeutic targets for controlling CAD." (PMID 22911112, 2012). "Though the exact role of IL-27 in atherosclerosis is unknown, it is reasonable to hypothesize that IL-27 may participate in atherosclerosis and that higher plasma IL-27 levels could be the new biomarker of CAD." (PMID 23285065, 2012). "This study provides further understanding of the pathogenesis of atherosclerosis: elevated IL-27 might be one of the important cytokines that compose a regulatory network in immunity and inflammation to affect atherosclerosis." (PMID 22911112, 2012). "Furthermore, because of its correlation with LPS-induced inflammation, IL-27 may also function as a possible marker or indication for atherosclerosis." (PMID 39844544, 2025). "Therefore, the effect of IL-27 on the process of atherosclerosis still remains a matter of debate." (PMID 38786961, 2024). "Hence, IL-27 may be an important target for the treatment and prevention of atherosclerosis and coronary artery disease." (PMID 32194399, 2020). "Therefore, further studies are needed to define the role of IL-35 and IL-27 in atherosclerosis." (PMID 31653058, 2019). "Moreover, data on IL-27 expression in clinical atherosclerosis are scarce." (PMID 29176764, 2017). "Thus, we propose an important proatherogenic role for IL27 in the early steps of atherosclerosis." (PMID 26663990, 2015). "However, little information is known about the role of IL-27 in atherosclerosis." (PMID 22911112, 2012). "IL-27 plays a crucial role in cardiovascular diseases (CVD), such as atherosclerosis, by primarily targeting inflammation." (PMID 39844544, 2025). "However, precise mechanisms of IL-27, especially in atherosclerosis remains unknown." (PMID 36405994, 2022). "The effect of IL-27 on NLRP3 inflammasome activation in monocytes, a pro-inflammatory mediator of atherosclerosis, was also very recently described." (PMID 29176764, 2017). "Based on these observations, we suggest that, in the context of the IL27-induced vascular inflammation, calprotectin might be a novel attractive candidate as a regulator of monocyte recruitment to early atherosclerotic lesions, hence preventing the progression of inflammation and atherosclerosis." (PMID 26663990, 2015). "In the context of the findings noted in animal models of atherosclerosis, oxidized LDL induced IL-27 expression likely represents a counter-regulatory mechanism to suppress inflammation in atherosclerosis." (PMID 25699211, 2015).
atherosclerosis (continued). "In conclusion, our findings clearly demonstrate that the cytokine IL27 plays an important role as a proinflammatory mediator by regulating the expression of endothelial genes and proteins, which may be mainly involved in the early stages of the atherosclerosis mechanism." (PMID 26663990, 2015). "Third, we did not directly investigate the effect of IL-27 on DCs in circulation and atherosclerotic plaques and the development of atherosclerosis in vivo." (PMID 22911112, 2012). "However, study on the effects of IL-27/anti-IL-27 antibody (anti-IL-27p28-Ab) administration to atherosclerosis model in ApoE−/− mice has not been reported." (PMID 36405994, 2022).
malaria (30 papers, 2011 to 2025). Malaria is a serious and sometimes fatal disease caused by a parasite that commonly infects a certain type of mosquito which feeds on humans. "This clinical malaria control is also associated with increased IL-7, IL-10, IL-17, and IL-27 plasma levels as well as IgG and better parasite clearance." (PMID 36293524, 2022). "IL-27 has been implicated in the regulation of IL-10 production by T cells during infection, such as in leishmaniasis and malaria." (PMID 28584007, 2017). "In fact, an association between the decrease in IL-28A, IL-27 levels in peripheral and placental plasma, IL-28A and IL-17E levels in cord plasma and the presence of malaria parasites or pigments in placenta tissue was observed (0.0001 ≤ P ≤ 0.02)." (PMID 27871325, 2016). "The genes Il27 and Il27ra were constitutively expressed in the liver, and their expressions were malaria-responsive, but only Il27ra was also significantly responsive to vaccination." (PMID 40243929, 2025). "It is mainly secreted by dendritic cells and macrophages, while CD4+ T cells also produce IL‐27 during chronic infection such as malaria and tuberculosis." (PMID 37855243, 2023). "Increased IFN-γ, CXCL10, CX3CL1, IL-18, and IL-27 levels were observed in malaria coinfections compared to HIV monoinfection." (PMID 36716305, 2023). "IL-6, IL-13, TNF-α, and IFN-γ were significantly higher in severe malaria, while IL-7, IL-10, IL-17, and IL-27 showed the opposite trend." (PMID 36293524, 2022). "(iv) IL-27, previously shown to be up-regulated in this malaria cohort, markedly induced a release of IL-18bp from endothelial cells in vitro, and notably, this presumably anti-inflammatory effect was counteracted by hemozoin." (PMID 34663245, 2021). "This was performed in the presence of IL-27, previously shown to be up-regulated in this malaria cohort." (PMID 34663245, 2021). "In malaria patients IL-27 levels were also negatively correlated with eGFR, reaching statistical significance in those co-infected with HIV." (PMID 31964363, 2020). "In experimental malaria, IL-27 has been suggested to regulate protective immunity partly through IL-27 producing CD4+ T cells." (PMID 31964363, 2020). "In the malaria patients as a whole, IL-27 levels were negatively correlated with platelets count independently of co-infection with HIV, indicating an association with platelet activation." (PMID 31964363, 2020). "Interleukin (IL)-27 is a pleiotropic cytokine exerting both inflammatory and anti-inflammatory effects, but data on IL-27 in malaria patients are scarce." (PMID 31964363, 2020). "In the context of experimental rodent malaria, IL‐27 (acting via the IL‐27 receptor) was shown to induce the generation of IL‐10‐expressing CD4+ T cells that were critical to limit immunopathology." (PMID 33282291, 2020). "A recent study demonstrated that malaria-specific CD4+ T cells produce IL-27 and regulate protective immunity during malaria parasite infection." (PMID 33584666, 2020). "In mouse models of malaria, a critical role for IL-27 signaling in the regulation of pro-inflammatory Th1 cell responses and suppression of immune-mediated pathology has been reported." (PMID 30809232, 2019). "In mouse models of malaria, IL‐27 is an important regulator of IL‐10 producing Type 1 regulatory T (Tr1) cells (Kumar, Ng, & Engwerda, 2019)." (PMID 31890299, 2019). "In the present study, low IL-27 levels were observed in endemic control group compared to malaria-naïve control group." (PMID 28118834, 2017). "A lower level of IL-27 was observed in endemic control group in comparison to malaria-naïve control group." (PMID 28118834, 2017). "IL-27 is a potent immune-regulatory cytokine capable of dampening inflammation in a broad range of diseases including malaria, Toxoplasma gondii and IAV infections, inflammatory arthritis and experimental allergic encephalomyelitis." (PMID 28953978, 2017).
malaria (continued). "In children infected with P. falciparum, IL-27 plasma levels were decreased during uncomplicated malaria in comparison to endemic control group." (PMID 28118834, 2017). "A recent study identified a novel subset of malaria antigen-specific, IL-27-producing regulatory CD4+ T cells in mice infected with Plasmodium berghei ANKA." (PMID 28255204, 2017). "This agrees with previously published work demonstrating that cytokines, including IL-10 and IL-27, are important in BM responses during rodent malaria and/or in malaria patients." (PMID 28938907, 2017). "IL-27 has been implicated in the induction of IL-10 production by Th1 cells in malaria and leishmaniasis; however, the role of IL-27 in regulating T cell production of IL-10 during M. tuberculosis infection is still unclear." (PMID 28584007, 2017). "A recent report indicated that a subset of regulatory CD4+ T cells produce IL-27 in response to malaria antigen recognition during infection." (PMID 28255204, 2017). "The IL-27-producing CD4+ T cells are forkhead box P3− CD11a+CD49d+ malaria antigen-specific CD4+ T cells, and they are distinct from IFN-γ-producing Th1 or IL-10-producing Treg cells." (PMID 27867385, 2016). "Previous work by others has already identified an important role for IL-27 in Tr1 cell development in experimental malaria and leishmaniasis." (PMID 26765224, 2016). "Recently, a unique subpopulation of malaria-specific CD4+ T cells was revealed to produce IL-27 in response to T-cell receptor stimulation, subsequently inhibiting IL-2 production and clonal expansion of other T cells." (PMID 27867385, 2016). "In other studies of experimental malaria, IL-27 appears to be an important cytokine for the development of protective immunity and may be essential for the development of IL-10-producing regulatory CD4 T-cells." (PMID 40972121, 2025). "IL-27 could be seen as an immunoregulatory cytokine in malaria, having a proinflammatory (induces IL-6 release) as well as an anti-inflammatory (inhibits IL-8 release) role." (PMID 34790829, 2021). "Based on experimental studies, it has been suggested that IL-27, potentially induced by the parasite itself, could play a regulatory role in the maintenance of the balance between anti-malaria protective and host damaging immune responses." (PMID 31964363, 2020). "IL-27 signalling and its role in limiting Th1 cell-mediated inflammation has been reported in many experimental settings, including, encephalomyelitis, inflammatory bowel disease, tuberculosis, trypanosomiasis, malaria and leishmaniasis." (PMID 33049000, 2020). "To test whether IL‐27 could indeed induce the CD4hiCD38hi cell population in vitro, we cultured PBMCs from healthy malaria‐naïve (Brisbane) volunteers with P. falciparum‐parasitised RBC extract for 14 days +/− recombinant human IL‐27." (PMID 33282291, 2020). "Thus, IL-27 is a major mediator of Tr1 cell development in mouse models of malaria, but to date, the main driver of Tr1 cell generation identified in humans infected with P. falciparum are type I IFNs." (PMID 30809232, 2019). "Multivariate analysis confirmed results of univariate analysis where the presence of malaria parasites or pigments in placenta tissue impression smears correlated with decrease levels of maternal IL-17E, IL-27 and IL-28A and neonate levels of IL-28A and IL-17E (0.0001 ≤ P ≤ 0.02)." (PMID 27871325, 2016). "Moreover, corroborating the reduction in the pro-inflammatory profile, we discovered higher expression of IL-10, TGF-β1 and IL-27 in both lymph nodes in the EAE-malaria mice relative to the EAE-alone mice." (PMID 21464982, 2011). "Additionally, in in vivo parasite infection models, IL-27 inhibits IFN-γ production and attenuates disease pathology associated with Toxoplasma gondii, Trypanosoma cruzi, Plasmodium berghei, Leishmania donovani, and malaria." (PMID 36405994, 2022).
malaria (continued). "We have recently shown increased IL-27 levels in this cohort of malaria patients potentially mediating both inflammatory and anti-inflammatory effects and our data in the present study suggest that IL-27 could balance the activity of the IL-18 system by increasing the level of IL-18bp." (PMID 34663245, 2021). "Herein, we have no data on the cellular sources of IL-27 in human falciparum malaria, but notably, IL-27 levels were strongly correlated with plasma levels of IP-10 and sCD25 in patients with falciparum malaria, further suggesting a relation of IL-27 to T cell activation in malaria." (PMID 31964363, 2020). "Thus, IL-27 is a critical regulator of IL-10 producing Tr1 cells in mouse models of malaria." (PMID 30809232, 2019). "Therefore, modulation of IL-10 production in malaria may be achieved by targeting the activities of upstream activating cytokines, such as IL-27, IL-21, type I IFNs, TNF, or TGFβ." (PMID 30809232, 2019). "In addition, some studies have shown that IL-27-producing CD4+ T cells may play a role in the regulation of protective immune response against malaria." (PMID 27871325, 2016). "Increased IFN-γ, IL-4, IL-10, IL-27, CXCL10, and CX3CL1 levels were observed in malaria monoinfection compared to HIV virus monoinfection." (PMID 36716305, 2023). "Other studies demonstrated that IL-28A and IL-27 cytokines induce the Th1 polarizing cytokines (IFN-γ and IL-12) that protect against malaria in human and animal models." (PMID 27871325, 2016). "Our study also shows that this second expansion phase of malaria‐specific CD4+ T cells is not a direct effect of IL‐27 inhibition, since inhibition with anti‐IL‐27 Ab starting 11 days of infection had no such effect." (PMID 37855243, 2023). "Thus, IL-27-producing regulatory CD4+ T cells, designated Tr27 cells, play a critical role in the regulation of protective immune responses against malaria parasites." (PMID 27867385, 2016). "With regard to PM infection, plasma levels of peripheral IL-28A, IL-27 and IL-17E were significantly lower in malaria infected than in malaria non-infected women." (PMID 27871325, 2016). "Finally, these findings show how the absence of IL‐27 enhances memory during malaria, suggesting potential applications in the development of vaccines and other strategic interventions." (PMID 37855243, 2023). "However, data on IL-27 regulation in clinical malaria is scarce, and to this end, there are no data on IL-27 levels during falciparum malaria in adults." (PMID 31964363, 2020). "Importantly, patients with HIV infection without co-infection with malaria show no significant changes in IL-27 levels during follow-up." (PMID 31964363, 2020). "(i) IL-27 was markedly up-regulated in malaria patients compared with controls and HIV-infected patients without malaria, showing no relation to HIV co-infection." (PMID 31964363, 2020). "Whereas there was a significant decline in IL-27 levels after 48 h, levels were still significantly increased as compared with HIV-infected patients without malaria and healthy controls." (PMID 31964363, 2020). "Furthermore, ICOS is linked to Tr1 development and activity, and recent studies show that systemic IL-27 and ICOS cooperate to regulate Tr1 activity during experimental malaria; however, in these reports neither IL-27R signaling nor ICOS was essential for Tr1 development during P. yoelii malaria." (PMID 27732671, 2016).
multiple sclerosis (30 papers, 2012 to 2025). A progressive autoimmune disorder affecting the central nervous system resulting in demyelination. "We obtained preliminary results in a pilot study in which we analyzed the possible role of the IL-27-T4730C polymorphism in Multiple Sclerosis." (PMID 35011777, 2021). "To date, to our knowledge, there are no studies investigating the relationships between IL-27-T4730C, IL-27-A964G, IL-23-R381Q gene polymorphisms and the risk of multiple sclerosis." (PMID 35011777, 2021). "Accordingly, the present study analyzed: (i) the potential association of these gene polymorphisms to multiple sclerosis susceptibility and (ii) the relationships of IL-27 and IL-23R SNPs with the clinical features of patients with multiple sclerosis." (PMID 35011777, 2021). "The present study analyzed the associations of IL-23 and IL-27 SNPs with susceptibility to multiple sclerosis." (PMID 35011777, 2021). "In human brains with lesions caused by multiple sclerosis, it has been shown that the pro-inflammatory cytokine environment increases the production of IL-27 levels from microglia." (PMID 32802395, 2020). "An association analysis of these haplotypes with odds of multiple sclerosis revealed that only GC (IL-27-A964G, IL-27-T4730C) was significantly associated with MS risk in the additive model with adjustment for age group (≤40 years vs. >40 years), sex and smoking." (PMID 35011777, 2021). "Likewise, low serum levels of IL-27 have been associated with multiple sclerosis and high production of IL-27 by PBMCs has been associated with a less severe disease course in IFN-β-treated MS." (PMID 25738751, 2015). "In fact, increase of IL-27 in cerebrospinal fluid of patients with multiple sclerosis correlates with suppression of neuroinflammation, underscoring therapeutic potential of IL-27 as treatment for human CNS autoimmune diseases." (PMID 37334383, 2023). "The data presented here provide unique insights into the biosynthesis and immunobiology of IL-27 cytokine and suggest that the i27-exosomes can be exploited as a stand-alone immunotherapy for CNS autoimmune diseases such as uveitis and multiple sclerosis." (PMID 37334383, 2023). "In the present study, we evaluated the haplotype frequencies of these two IL-27 SNPs in both multiple sclerosis patients and healthy controls." (PMID 35011777, 2021). "Th17-lymphocytes are highly efficient producers of IL-21, IL-22, and especially IL-27; cytokines widely associated with the development of pathologies such as Systemic Lupus Erythematosus (SLE), RA, and Multiple Sclerosis (MS)." (PMID 32384594, 2020). "Our results are in line with those described in previous reports in which there was a lower serum expression of IL-27 in patients with active systemic lupus erythematosus, multiple myeloma and multiple sclerosis." (PMID 24887071, 2014). "Investigators examined the expression patterns of IL-27 subunits in brain specimens from patients diagnosed with multiple sclerosis (MS) and compared them with control samples from neurologically healthy donors without any clinical or neuropathological signs of central nervous system disorders." (PMID 41561993, 2025). "The interaction between IL-27 and IL-10 was also demonstrated in experimental autoimmune encephalomyelitis, a model commonly engineered in rodents and other small animals to study multiple sclerosis." (PMID 32802395, 2020). "The purpose of this study was to examine whether myeloid dendritic cells (mDCs) from patients with multiple sclerosis (MS) and healthy controls (HCs) become similarly tolerogenic when exposed to IL-27 as this may represent a potential mechanism of autoimmune dysregulation." (PMID 37175706, 2023). "Interferon-β-treated multiple sclerosis patients had increased IL10 and IL27 gene expression levels in monocytes in vivo." (PMID 25738751, 2015).
multiple sclerosis (continued). "IL-27 subunit expression was investigated in brain tissue obtained from individuals with Multiple Sclerosis (MS) and donors without clinical and neuropathological evidence of CNS disease (control samples)." (PMID 38966644, 2024).